INS (insulin)
Diseases named in the same sentence as INS in open-access papers (continued):
Sharing a sentence is not in itself a finding about the gene and the disease.
type 2 diabetes (continued). "In pregnancy, women with Type 2 diabetes are typically advised to conduct self‐monitoring of blood glucose levels, with additional advice on diet and exercise, and treatment with metformin and/or insulin to optimise blood glucose management." (PMID 39527377, 2025). "All participants had type 2 diabetes, and 60% were receiving insulin treatment." (PMID 41040742, 2025). "In study IV, we examined whether 8 weeks of HIIT changed the insulin-mediated suppression of plasma BCAAs in individuals with type 2 diabetes, glucose-tolerant individuals with obesity and lean individuals." (PMID 40404819, 2025). "Therefore, to minimize this effect, in youth with type 2 diabetes, metformin and long‐ or intermediate‐acting insulin were discontinued 48 h prior to the clamp, as has been reported previously." (PMID 40470991, 2025). "In mice, this specific microRNA has been associated with disturbances in glucose metabolism and alterations in insulin sensitivity, and it was also hypothesized to be involved in the development of diabetes type II in humans." (PMID 40510676, 2025). "Previous research supports this, as a study involving 20-minute submaximal heart rate cycling or running exercises, coupled with 20-minute warm-up/cool-down sessions three times a week for four weeks, revealed reduced insulin resistance and blood glucose levels in individuals with type 2 diabetes." (PMID 39136513, 2025). "One patient in the cohort had type II diabetes and was on insulin and metformin." (PMID 40424308, 2025). "The subgroups using non-insulin GLD are likely to consist of persons with type 2 diabetes." (PMID 41350985, 2025). "Switching from insulin to GLP-1/GIP receptor agonists (e.g., tirzepatide) may benefit patients with type 2 diabetes, especially those needing weight loss, better glycemic control, or reduced hypoglycemia." (PMID 40746803, 2025). "Our study provides further evidence that fasting glucose regulation is not only influenced by the timing and nutrient composition of the evening meal, but also by nocturnal metabolic processes and insulin sensitivity in individuals with prediabetes and diet and/or metformin type 2 diabetes." (PMID 40573137, 2025). "Although previous animal studies have shown that peripheral levodopa is correlated with insulin secretion in pancreatic beta cells, the mechanism by which the pancreas uses levodopa differently in humans with obesity and type 2 diabetes remains unknown." (PMID 40099262, 2025). "During type 2 diabetes, the pancreas initially tries to compensate for insulin resistance, but factors such as obesity and sedentary lifestyles lead to failures among beta cells and decreased insulin production, resulting in high glucose levels." (PMID 41304970, 2025). "Two-thirds (111/166, 66.9%) reported type 2 diabetes, and 50% (83/166) used insulin." (PMID 40266665, 2025). "Consequently, in the early phases of development of type 2 diabetes, fasting insulin levels in people with type 2 diabetes with fasting blood glucose levels > 140 mg/dL (7.8 mmol/L) were nine-fold higher than in lean people with normal fasting glucose levels." (PMID 41009753, 2025). "The diagnosis is based on evidence of hepatic steatosis, confirmed via imaging or histology, along with at least one of the following: overweight or obesity, type 2 diabetes mellitus, or metabolic dysfunction—such as dyslipidemia, elevated blood pressure, or insulin resistance." (PMID 40729034, 2025). "Therefore, this damage can disrupt insulin’s capacity to control blood glucose levels, thereby contributing to insulin resistance, which is a key determinant in the development of type-2 diabetes." (PMID 41191622, 2025). "Changes in pancreatic insulin secretion and insulin sensitivity may arise many years before the development of type 2 diabetes." (PMID 41009753, 2025).
type 2 diabetes (continued). "Additionally, selenium intake has been associated with favorable glycemic markers, such as lower HbA1c and insulin levels, indicating its potential role in glucose metabolism and type 2 diabetes management." (PMID 40732969, 2025). "This immensely common disorder in the human population, type 2 diabetes, is characterized by the pancreatic β-cells losing their functionality and the development of resistance to insulin in specific target tissues, thus, being defined as comparative insulin insufficiency." (PMID 40284169, 2025). "In a study of 42 obese patients with type 2 diabetes, amlexanox treatment administered as 50 mg tablets three times per day for 12 weeks resulted in a reduction of haemoglobin A1c levels and in a subgroup improved insulin sensitivity and hepatic steatosis." (PMID 40341181, 2025). "Mechanistically, selenoproteins regulate insulin secretion and action, though imbalances such as overexpression of selenoprotein P may paradoxically impair insulin sensitivity and contribute to type 2 diabetes pathogenesis." (PMID 41280964, 2025). "Targeting these mechanisms through vitamin D supplementation could potentially improve insulin sensitivity, reduce cellular damage, and enhance mitochondrial health, offering a valuable approach for the management and prevention of type 2 diabetes." (PMID 40076782, 2025). "In individuals with type 2 diabetes (T2D) seasonal changes in insulin sensitivity have been observed and it may be partially mediated by alterations in the gut microbiota, particularly through changes in SCFA production and gut barrier function." (PMID 41156845, 2025). "Similarly, quercetin has shown potential as a treatment for type 2 diabetes by enhancing insulin secretion and sensitivity." (PMID 40365311, 2025). "Moreover, within the hospital-based multidisciplinary setup, diabetic patients were more commonly undergoing treatment with insulin, even considering only individuals with type 2 diabetes." (PMID 39160371, 2025). "Conversely, findings in this study propose that the cerebellar vermis may be influenced by sensitivity to insulin, decreasing its glucose metabolism in Type 2 diabetes, which also seems to play a role in CD." (PMID 40510539, 2025). "GLP-1RAs are approved by the U.S. Food and Drug Administration for managing type 2 diabetes and obesity through multiple mechanisms, including enhanced insulin secretion, glucagon suppression, delayed gastric emptying, and modulation of central appetite pathways." (PMID 41303457, 2025). "Surprisingly, in type 2 diabetes, genes positively correlated with exocytosis were upregulated whereas those negatively correlated were downregulated, possibly reflecting compensatory adaptation to increased insulin demand." (PMID 40768044, 2025). "Both insulin efsitora alfa and insulin icodec offer simplified regimens with promising efficacy and safety profiles, as demonstrated in multiple recent phase 3 trials conducted in patients with type 2 diabetes." (PMID 40937414, 2025). "DPP-IV is known to regulate insulin secretion in type 2 diabetes, supporting the notion that GDM and type 2 diabetes share mechanistic similarities at the EV level, and that placental EV cargo contains bioactive molecules that regulate maternal insulin secretion." (PMID 40852594, 2025). "Finally, treatment with arginine resulted in improved insulin sensitivity in type 2 diabetes patients, indicating ties between arginine metabolism and insulin signaling." (PMID 40985218, 2025). "Hyperglycemia, typically occurs in both type 2 diabetes (T2D), characterized by insulin resistance, and type 1 diabetes (T1D), which results from autoimmune destruction of pancreatic β cells responsible for insulin production." (PMID 41150749, 2025).
type 2 diabetes (continued). "Interventions such as probiotic and prebiotic supplementation, as well as fecal microbiota transplantation (FMT), have shown efficacy in restoring eubiosis and improving glycemic control, insulin sensitivity, and inflammatory parameters in individuals with MetS or type 2 diabetes mellitus (T2DM)." (PMID 40564061, 2025). "In addition, several pathways involved in the regulation of energy metabolism were enriched, such as type II diabetes mellitus, insulin secretion, glycolysis/gluconeogenesis, and the TCA cycle." (PMID 39858153, 2025). "This impairment leads to a reduction in insulin secretion, which is insufficient to meet the body’s requirements for glycemic control, thereby exacerbating hyperglycemia and contributing to the pathogenesis of type 2 diabetes mellitus." (PMID 40376582, 2025). "Similarly, we found that the DASH diet led to improvements in various cardiometabolic markers, as well as daily insulin usage among individuals with insulin-treated type 2 diabetes." (PMID 40062050, 2025). "Although we demonstrate the exclusion of mitochondrial GCN5L1 in HFD‐fed mouse model, further investigation on GCN5L1 translocation and the underlying mechanism in human patients with type 2 diabetes and MASLD is needed to unveil the function of mitochondrial GCN5L1 in insulin sensitivity." (PMID 41001747, 2025). "Similarly, fibroblast growth factor 21 (FGF21) analogs, such as pegbelfermin, have progressed into clinical development, showing beneficial effects on lipid metabolism, insulin sensitivity, and hepatic steatosis in obese individuals with type 2 diabetes." (PMID 40699742, 2025). "Our meta‐analysis of six RCTs involving almost 4000 adults with type 2 diabetes demonstrates that once‐weekly insulin efsitora alfa provides glycemic efficacy comparable to once‐daily insulin, with similar reductions in HbA1c, fasting plasma glucose, body weight, and achievement of HbA1c targets." (PMID 41152194, 2025). "pointed out that the gut microbiome might affect blood glucose regulation, insulin sensitivity, and other aspects, and thus was closely related to the incidence of metabolic diseases such as obesity and type 2 diabetes." (PMID 40799936, 2025). "Overall, available data indicate that various forms of IF, both those based on meal restriction (TRF, eTRF) and intermittent energy deficit (ADF, 5:2), lead to improved glycemic control, decreased glycated hemoglobin, and improved insulin sensitivity in people with type 2 diabetes and prediabetes." (PMID 41458802, 2025). "Although we used a mild STZ-induced diabetic mouse model that mimics certain aspects of type 2 diabetes, the inclusion of additional insulin-resistant or diet-induced models in future studies could enhance generalizability." (PMID 40770064, 2025). "Additionally, Rg1 contributes to regulating glucose metabolism and insulin sensitivity, suggesting benefits in type 2 diabetes management by reducing hyperglycemia-induced inflammation and improving pancreatic β-cell function." (PMID 40709093, 2025). "Training can improve insulin sensitivity in individuals with type 2 diabetes, but some patients who engage in exercise may fail to achieve the anticipated improvements in glycaemic control." (PMID 40413649, 2025). "Type 1 diabetesis characterized by severe insulin deficiency resulting from chronicand progressive destruction of pancreatic β-cells by the immunesystem, while in type 2 diabetes, the pancreas makes less insulinprogressively with time and the body becomes resistant to insulin." (PMID 40978378, 2025). "In the COMBINE 1 trial (NCT05352815), IcoSema showed superior efficacy on HbA1c reduction compared to icodec alone (-1.55% vs. -0.89% at 52 weeks; treatment difference -0.66%, 95% CI -0.76 to -0.57) in 1291 adults with type 2 diabetes inadequately controlled on daily basal insulin." (PMID 40937414, 2025).
type 2 diabetes (continued). "Cellular and animal studies demonstrated that LXA4 may directly affect the adipocyte insulin signaling pathway, potentially delaying the development of type 2 diabetes mellitus (T2DM)." (PMID 40862723, 2025). "In the case of UCEC, insulin has been linked to tumor development through the PI3K/Akt and RAS/MAPK pathways, which further elaborates the potential anticancer effects of metformin, a common treatment for type 2 diabetes, through the RAS/MAPK pathway." (PMID 39954675, 2025). "Normalization of insulin secretion is important for elder type 2 diabetes patients." (PMID 40317718, 2025). "The insulin and glucose impairment induces type II diabetes development." (PMID 39859502, 2025). "•Activating PAKs in adipocytes may help treat type 2 diabetes by reducing lipolysis and improving insulin sensitivity." (PMID 40659091, 2025). "In study II, we evaluated whether prior acute exercise altered insulin’s ability to suppress plasma BCAA levels in individuals with type 2 diabetes and glucose-tolerant individuals with obesity." (PMID 40404819, 2025). "Similarly, insulin icodec has demonstrated robust efficacy, with superior glycaemic outcomes in both insulin-naïve and insulin-experienced populations with type 2 diabetes, as shown in the ONWARDS programme." (PMID 40937414, 2025). "When blood glucose levels further rise into the range of overt type 2 diabetes, glucose-induced pancreatic insulin secretion may progressively decline due to exhaustion of the pancreatic beta cells." (PMID 41009753, 2025). "The majority of participants in the RCT had type 2 diabetes and were receiving insulin therapy." (PMID 40587847, 2025). "Over time, the pancreas in individuals with type 2 diabetes may gradually lose its ability to produce insulin effectively." (PMID 41009460, 2025). "Patients with type 1 diabetes require insulin therapy, whereas those with type 2 diabetes usually start with changes in diet and exercise along with medications, and may eventually require insulin treatment." (PMID 41009460, 2025). "Although the alloxan model offers valuable insights into hyperglycemia and β‐cell‐related interventions, its ability to reflect the complex metabolic disturbances involved in Type 2 diabetes, including insulin resistance, systemic inflammation, and lipid metabolism disorders, is limited." (PMID 40905017, 2025). "This may represent a compensatory mechanism to maintain quasi‐hyperinsulinemia to counterbalance the defect in β‐cell function, ~78% decline in DI, and ~46% decline in first‐phase insulin secretion in the presence of type 2 diabetes." (PMID 40470991, 2025). "Moreover, IL-6 is involved in regulating insulin action, and elevated levels of IL-6 in obesity are a predictive factor for developing type 2 diabetes." (PMID 40458085, 2025). "The beneficial impact of exercise on glycemic control in individuals with type 2 diabetes may be attributed to its ability to increase glucose uptake mediated by insulin and the quantity of glucose transporters (GLUT4) through specific signaling pathways." (PMID 39136513, 2025). "Interventional clinical trials have corroborated these findings, demonstrating that dietary BCAA restriction reduces plasma BCAA levels, decreases fasting insulin concentration, and improves insulin sensitivity in both healthy volunteers, and those with type 2 diabetes." (PMID 41117265, 2025). "Se‐CMP has significantly alleviated insulin‐resistant properties and may be a natural anti‐IR source for managing Type II diabetes mellitus." (PMID 40351361, 2025). "Insulin is anabolic to bone and hyperinsulinemia in type 2 diabetes may offset bone fragility resulting from hyperglycemia in early disease, with the negative effect predominating with longer duration." (PMID 40643204, 2025).
type 2 diabetes (continued). "This could be due to a genetic abnormality in the functioning of β cells in the pancreas that produce insulin, known as Type 1 Diabetes, or the denaturation of the insulin receptor, known as Type 2 Diabetes (T2D)." (PMID 39833933, 2025). "Tirzepatide enhances glucose-dependent insulin secretion, reduces glucagon levels, delays gastric emptying, and improves insulin sensitivity, making it a promising therapeutic option for managing both hyperglycemia and obesity in patients with type 2 diabetes." (PMID 40864047, 2025). "We retrospectively analyzed eight weeks of data from 52 participants (adults with type 1 diabetes and adults with insulin-treated type 2 diabetes) recruited to two single-center randomized controlled studies using FCL insulin delivery during unrestricted-living conditions." (PMID 38613227, 2025). "Therefore, given its ability to enhance insulin sensitivity and improve glucose uptake, PPARγ is a major therapeutic target for treating type 2 diabetes." (PMID 40286240, 2025). "Additionally, a pilot randomized controlled study that compared sitagliptin monotherapy and its combination with basal insulin in hospitalized type 2 diabetic patients, demonstrating comparable efficacy and safety profiles for both treatment strategies." (PMID 40901501, 2025). "The resultant immune activation, combined with reduced insulin sensitivity in adipocytes, promotes excessive release of free FAs, which in turn stimulate hepatic gluconeogenesis, ultimately contributing to hyperglycaemia and the progression of type 2 diabetes." (PMID 41009610, 2025). "In type 2 diabetes, insulin resistance develops, reducing tissue sensitivity to insulin." (PMID 40507946, 2025). "Thus, despite similar weight loss after bariatric surgery in these two well-matched groups, weight loss specifically decreased excess pancreatic triglyceride content and the first-phase insulin response in the group with type 2 diabetes." (PMID 41009753, 2025). "It is known that the enzyme acts as a negative regulator of insulin signaling, and hence, it could be a pharmacological target for the treatment of type 2 diabetes and obesity." (PMID 40286074, 2025). "Moreover, marine collagen peptides have been reported to improve glucose metabolism and insulin sensitivity in type 2 diabetic rats, likely through the reduction in oxidative stress and inflammation, and upregulation of GLUT4 and PPAR-α expression." (PMID 41009711, 2025). "Patients with type 1 diabetes showed a higher level of adherence to recommendations than those with type 2 diabetes, which may result from intensive education on insulin therapy." (PMID 41358226, 2025). "Interventions promoting regular physical activity, balanced dietary habits, smoking cessation, alcohol moderation, adequate sleep, and stress reduction have demonstrated efficacy in improving insulin sensitivity and preventing the progression to type 2 diabetes." (PMID 40648978, 2025). "Nicotinamide adenine dinucleotide phosphate (NADPH) oxidase (NOX), a producer of reactive oxygen species (ROS), acts as a key generator of oxidative stress within pancreatic islet β-cells, significantly affecting glucose-induced insulin release and β-cell viability in Type 1 and Type 2 diabetes." (PMID 39995417, 2025). "Both PPGR and FG are interrelated; PPGR levels have a substantial impact on HbA1c in well-controlled, non-insulin-treated type 2 diabetes patients, and a diet targeting the limitation of PPGR was shown to improve overall glycemic control in individuals with prediabetes." (PMID 40573137, 2025). "In type 2 diabetes, the body produces an insufficient amount of insulin." (PMID 40281899, 2025). "We hypothesized that canagliflozin would reduce insulin initiation and dose intensification in patients with type 2 diabetes and CKD." (PMID 40036884, 2025).